FASN (fatty acid synthase)
Diseases named in the same sentence as FASN in open-access papers (continued):
Sharing a sentence is not in itself a finding about the gene and the disease.
cancer (continued). "The present study supports FASN as a novel target for cancer therapy and provides a theoretical foundation for the clinical application of Coix seed extract in cancer therapy." (PMID 24778702, 2014). "Recent evidence shows that during de novo fatty acid synthesis, fatty acid synthase plays a crucial role in the carcinogenesis process of various cancers." (PMID 24979135, 2014). "Elevated expression of FASN has been found in the earliest stages of cancer development and becomes more pronounced during tumor progression." (PMID 25313139, 2014). "Inhibition of FASN in cancer cells has been found to induce apoptosis, which suggests that inhibiting intracellular FASN should be a reasonable way for the treatment of cancer." (PMID 25009654, 2014). "Additional studies concluded that AMPK agonists are effective in the treatment of cancer, while other studies showed that the lipogenic enzyme fatty acid synthase (FASN) is regulated by energy intake and plays a crucial role in carcinogenesis." (PMID 24960186, 2014). "Several studies have demonstrated that suppression of FASN activity promotes apoptosis in cancer cells." (PMID 25255125, 2014). "Research has shown that FASN is highly expressed in the hepatocytes and adipocytes of obese patients and in various kinds of cancer cells." (PMID 24778702, 2014). "Highly proliferating cancer cells use fatty acids (either synthesized endogenously by FASN or supplied exogenously from the microvascular system) predominantly for the synthesis of phospholipids, which are then incorporated in cell membranes." (PMID 24932311, 2014). "As such, FASN is highly expressed in various types of human cancers and in several cancer types elevated FASN expression is linked to poor prognosis." (PMID 24932311, 2014). "Here, our present work strongly suggests that the apoptotic mechanism of capsaicin provides a novel therapeutic intervention as a selective anti-cancer agent that potentially targets the lipogenic enzyme FASN in HepG2 cells." (PMID 25255125, 2014). "Overexpression and hyperactivity of lipogenic enzymes, such as ACC1 and FASN, have been shown to be critical in the growth and survival of cancer cells." (PMID 25502566, 2014). "Previous studies have shown that FASN expression and its activity in normal cells are many times lower than that in cancer cells." (PMID 25255125, 2014). "This study demonstrates the selective anti-cancer effect of capsaicin on HepG2 cells that express higher levels of FASN than normal cells." (PMID 25255125, 2014). "In this study, we investigated the role of a FASN inhibitor combined with an mTOR inhibitor in cancer cell growth." (PMID 24866893, 2014). "FASN has been described as a possible target for chemotherapy because its expression is low or absent in most normal tissues and, in contrast, is high in a significant variety of human malignant tumors, where FASN plays important roles in proliferation." (PMID 24964211, 2014). "As a result of over-expression of FASN protein and its activity, cancer cells exhibit the high requirements of fatty acid products for the synthesis of membrane phospholipid." (PMID 25255125, 2014). "Another research has shown that, after FASN inhibition, the growth of the cancer cell remains at G0 phase, showing that fatty acid synthesis is related to cancer cell cycle." (PMID 24778702, 2014). "Fatty acid synthase (FAS) is highly expressed in various types of cancer, and elevated expression of FAS has been suggested to be a predictor of tumor aggressiveness and poor prognosis." (PMID 24422874, 2014). "The use of capsaicin as a source for a new FASN inhibitor will provide new insight into its possible application as a selective anti-cancer therapy." (PMID 25255125, 2014). "FASN appears to play a key role in tumor initiation and propagation for a number of malignancies, and represents an attractive target for cancer treatment." (PMID 25009654, 2014).
cancer (continued). "The recent discovery of human cancer cells expressing high levels of fatty acid synthase and undergoing significant endogenous fatty-acid synthesis has allowed researchers to perform in-depth reviews of the roles of fatty acids in tumor biology." (PMID 23560043, 2013). "Most efforts to pharmacologically inhibit lipid synthesis have focussed on FASN, and the effects of inhibitors of this enzyme have been investigated in different preclinical cancer models." (PMID 24203995, 2013). "Together these data confirm the important role of FASN in cancer development, maintenance, and progression." (PMID 22886728, 2013). "It has been shown that the growth factors, hormones and activation of their receptors increased FASN transcription in cancer cells." (PMID 23725225, 2013). "Human cancer cells have elevated levels of FASN and undergo exacerbated endogenous fatty acid synthesis independent of regulatory signals that downregulate fatty acid synthesis in normal cells." (PMID 23292678, 2013). "Various reports have shown that inhibiting expression of FASN suppresses cancer cell proliferation in vitro and in vivo." (PMID 23599729, 2013). "Although extensive research has been carried out to investigate the potential of FASN as a promising therapeutic target for cancer treatment, limited studies are available on the metabolic consequences of FASN inhibition in cancer cells." (PMID 22886728, 2013). "Recent evidences indicate that cancers with high expression of FASN always undergo a significant endogenous fatty acid biosynthesis and display a biologically aggressive subset." (PMID 23725225, 2013). "Recent studies showed that FASN is primarily expressed in hormone-sensitive cells, promote cell proliferation and that the inhibition of FASN effectively and selectively kills cancer cells." (PMID 24391718, 2013). "For instance, inhibitors of fatty acid synthase, which can be overexpressed in cancer, are being investigated for their ability to affect cancer growth." (PMID 24098742, 2013). "De novo fatty acid synthesis is a cancer therapy target and the drug Orlistat and several other drugs target the fatty acid synthase (FASN) enzyme while other cancer drugs target ATP citrate lyase (ACLY)." (PMID 24958139, 2013). "The higher expression in cancer cells of the FAS I complex (fatty acid synthase) is well known, however the function of the identified sub-networks seems to go well beyond the synthesis of lipids as biomass building blocks." (PMID 24154670, 2013). "Pharmacologic inhibition of FASN by small molecule inhibitors or down-regulation of FASN gene expression by RNAi results in apoptosis of cancer cells, inhibition of tumor growth, and prolongation of survival of tumor-bearing animals." (PMID 22886728, 2013). "FASN is over-expressed in several human cancers, including prostate, breast, lung, ovary, bladder, stomach, oral cavity and melanoma, and the over-expression is associated with poor prognosis." (PMID 23741342, 2013). "Elevated FASN expression in cancer cells seems to modulate lipid raft domains and various biological processes which in turn prevent apoptosis and promote cell survival." (PMID 23725225, 2013). "Further evidence for lipid biosynthesis in cancer cells was provided by the observation that a tumour-specific antigen, OA-519, is indeed FASN." (PMID 24203995, 2013). "A number of chemical inhibitors of lipid biosynthesis, most prominently inhibitors of FASN, have been investigated in preclinical cancer models or are entering clinical trials." (PMID 24203995, 2013). "Inhibitors of FASN, such as orlistat, reportedly show antitumor effects against cancers that over-express FASN, making FASN a promising therapeutic target." (PMID 23741342, 2013). "As a large protein with a complex structure and multiple catalytic domains, FASN is considered as an important metabolic enzyme and a potential target in human cancers." (PMID 23725225, 2013).
cancer (continued). "An interesting point is the increase in fatty acid synthesis which in many cancer cell lines is accompanied by increased fatty acid synthase (FASN) capacity and contributes to tumoral cell development." (PMID 22654896, 2012). "The mechanisms by which FASN is upregulated in cancer cells have been described in a number of epithelial malignancies." (PMID 22485149, 2012). "The down-regulation of fatty acids seems to contradict the up-regulation of fatty acid synthase (FASN) and increased de novo fatty acid synthesis that is found in many cancers." (PMID 22823888, 2012). "Due to established roles of FASN overexpression in tumor growth and malignancy, targeting on fatty acid de novo synthesis for cancer therapy had been intensively explored." (PMID 23166793, 2012). "Enzyme fatty acid synthase (FASN) that shows cancer specifically expressed in our practice is a key metabolic enzyme in energy homeostasis and has been found up-regulated in different malignant tumors." (PMID 22920603, 2012). "EGFR/PI-3Kinase enhances lipogenesis in cancer cells by activating lipogenic fatty acid synthase (FASN) machinery in conjunction with PPAR γ." (PMID 22509304, 2012). "Since previous reports have shown that FASN can be regulated by the mTor signaling pathway and USP2a-induced protein stabilization in cancer cells, we asked if the effect on FASN expression mediated by β-catenin involves these two pathways." (PMID 22485149, 2012). "Because of its relative abundance in cancer cells, fatty-acid synthase has been pursued as an oncology target." (PMID 22457791, 2012). "Levels of FASN expression in different human carcinomas attracted considerable interest of this enzyme as a target for therapy." (PMID 22769244, 2012). "Further studies will be required to delineate the biological and translational roles of FASN in drug resistance in ovarian and perhaps other types of cancers." (PMID 20508725, 2010). "It was almost half a century ago when the up-regulation of fatty acid synthase (FASN) was first described in cancer, which is now known to be over-expressed in the majority of cancers." (PMID 21042593, 2010). "More importantly, in patients with this cancer, the level of FASN expression significantly correlates with worse clinical outcome, supporting the view that FASN expression contributes to disease aggressiveness in cancer cells." (PMID 20508725, 2010). "Our indirect demonstration that Mb is likely to be regulated by intracellular FA levels, as shown by the inhibition of FASN, now indicates a putative role for Mb in FA metabolism of cancer cells and clearly warrants further study." (PMID 20531416, 2010). "Suppressing FASN enzyme activity with its inhibitor induces apoptosis in cancer cells that are resistant to paclitaxel and carboplatin." (PMID 20508725, 2010). "Fatty acid synthase catalyses the synthesis of unbranched FAs and is upregulated in the broad majority of malignant tumours." (PMID 20531416, 2010). "FASN is highly expressed in most human cancers and its inhibition leads to selective apoptotic death of cancer cells both in vitro and in vivo." (PMID 20707918, 2010). "In cancer cells, transcriptional regulation of FASN gene is one of the important mechanisms of FASN overexpression." (PMID 19352381, 2009). "Recently, it was reported that FASN inhibition induces endoplasmic reticulum stress in cancer cells, and FASN inhibitors cooperate with the endoplasmic reticulum stress inducer to enhance tumour cell death." (PMID 19352381, 2009). "FASN is not only overexpressed in cancer, but it also plays an essential role in tumour growth and survival." (PMID 19352381, 2009). "Further studies are needed to clarify these points for effective application of the FASN inhibition strategy to cancer therapy." (PMID 19352381, 2009). "The pro-apoptotic effects of AMPK activation in various cancer cells includes inhibition of fatty acid synthase and induction of stress kinase and caspase-3." (PMID 18474106, 2008).
cancer (continued). "Second, FASN has the ability to regulate specifically the activity and/or expression of key cancer-related signalling networks of growth factors and their receptors, as well as of steroid hormones and their receptors." (PMID 18947424, 2008). "Concomitantly, fatty acid synthase (FASN), which catalyzes the massively observed lipogenesis in cancer cells, was suggested to represent a metabolic oncogene." (PMID 19812737, 2008). "FASN is also expressed in early stages of tumor development or pre-cancer lesions such as colonic adenoma, dysplastic squamous epithelium, and carcinoma of the tongue, although this up-regulation is more pronounced in the late stages of tumors." (PMID 18523653, 2008). "Inhibitors of FASN have been found to induce apoptosis in cancer cells that have high levels of FASN." (PMID 18523653, 2008). "It is predictable that up-regulated expression of FASN and increased levels of FAs observed in different cancer types would compromise cell response to DNA damage, thus promoting tumorigenesis." (PMID 18523653, 2008). "The lipogenic enzyme fatty acid synthase (FAS) is up-regulated in a wide variety of cancers, and is considered a potential metabolic oncogene by virtue of its ability to enhance tumor cell survival." (PMID 17565694, 2007). "Up-regulation of fatty acid synthase (FAS), the enzyme responsible for the endogenous synthesis of palmitate, is increasingly recognized as a hallmark of cancer." (PMID 17565694, 2007). "Furthermore, lipid metabolism is rewired in cancer, for instance, by upregulating fatty acid synthase (FASN), the major enzyme regulating fatty acid metabolism, which is now considered a novel target for cancer patients." (PMID 41131959, 2026). "In the context of HER2 + BC, FASN upregulation was also related to cancer progression." (PMID 40133809, 2025). "FASN is involved in the production of phospholipids required for cancer cells." (PMID 40733158, 2025). "Researchers have developed and tested compounds aimed at FASN in various cancer models." (PMID 40487761, 2025). "Moreover, FASN inhibitors can block palmitoylation and plasma membrane- and mitochondria-associated EGFR activation and enhance cancer cell sensitivity to EGFR inhibitors by promoting EGFR ubiquitination, which further results in attenuating tumor growth." (PMID 41306968, 2025). "Therapeutic agents that can block the SREBP1/FASN lipogenic pathway may effectively “starve” cancer cells of crucial lipid resources and prevent metastatic progression." (PMID 40942159, 2025). "One reason healthy cells are less impacted by FASN inhibition might be their lower metabolic load than cancer cells." (PMID 40133683, 2025). "Notably, FASN has also been identified as a therapeutic target in diverse cancer types, with its inhibition leading to tumor suppression." (PMID 41210688, 2025). "FASN is under active investigation as a potential target for cancer therapies." (PMID 39971971, 2025). "Indeed, the expression of IGF1R, IGF2R, FGFR2-4, and de novo fatty acid biosynthetic enzymes (ACC1, FASN) correlates with ferroptosis resistance across 824 primary, adherent cancer cell lines." (PMID 40000627, 2025). "In addition, estrogens, through both classical ERs and the G protein-coupled estrogen receptor (GPER), upregulate FASN, important for cancer cell growth and survival." (PMID 40427160, 2025). "FASN is frequently overexpressed in tumors and participates in cancer cell proliferation." (PMID 40684943, 2025). "Considering the PFL linking HER2 with FASN, pharmacological inhibition of HER2 could also be sufficient to inhibit FASN activity, thus forcing cancer cells to uptake FAs from the extracellular microenvironment." (PMID 39833955, 2025).
cancer (continued). "Notably, 1,25-dihydroxyvitamin D3 and its analogs have been shown to inhibit FASN expression and alter fatty acid metabolism in prostate, ovarian, and colon cancer cells." (PMID 40872626, 2025). "Furthermore, FASN and SCD1, both associated with fatty acid metabolism, were significantly upregulated in primary cancer and CRPC samples." (PMID 39988626, 2025). "FASN can also inhibit OGA in U2OS cells under oxidative stress to promote cancer cell survival." (PMID 40684943, 2025). "Numerous studies have confirmed the potential of FASN as a target for anti-cancer therapy." (PMID 40263296, 2025). "FASN was considered as a potential target to block lipogenesis, including cancers." (PMID 40180937, 2025). "Rapidly proliferating cancer cells require a continuous supply of membrane phospholipids and signaling lipids, which is largely met by the upregulation of key lipogenic enzymes such as fatty acid synthase (FASN) and acetyl-CoA carboxylase (ACC)." (PMID 41350297, 2025). "Metabolic inhibitors targeting fatty acid synthase or glycolytic enzymes may reduce the ability of cancer cells to endure radiation and EMT." (PMID 40895189, 2025). "Suppression of de novo lipogenesis via FA synthase (FASN) inhibition was shown to attenuate CD44 expression, possibly through its palmitoylation, highlighting the association between lipid metabolism and cancer stemness." (PMID 40882371, 2025). "Importantly, disease-free survival was significantly reduced in cases of combined ATF6 and FASN amp/gain compared to those showing ATF6-only amp/gain in the Pan-Cancer Atlas (P = 0.0394), with a trend observed in the TCGA database (P = 0.4046)." (PMID 40890536, 2025). "FASN, the key enzyme de novo lipogenesis, is frequently overexpressed in cancers." (PMID 40735642, 2025). "It has been well-established that FASN overexpression and/or activation plays an important role in promoting tumorigenesis through lipogenesis to provide fatty acids for membrane synthesis and energy for cancer cells." (PMID 39971971, 2025). "Meanwhile, targeting FASN and sphingosine kinases has emerged as a promising therapeutic avenue in hematologic malignancies, which has demonstrated potential in disrupting lipid metabolism to impair cancer cell survival." (PMID 41345744, 2025). "Regarding lipid metabolism, microbiota may modulate the expression of key enzymes such as fatty acid synthase (FASN), thereby promoting de novo lipid synthesis to enhance membrane construction and signalling capabilities in cancer cells." (PMID 41031610, 2025). "Cancer cells often exhibit FASN hyperactivity to meet increased demands for long-chain fatty acids, which are incorporated into membrane lipid rafts essential for modulating growth factor-mediated oncogenic pathways involved in cell survival, proliferation, migration, and invasion." (PMID 40733158, 2025). "Moreover, FASN inhibitor treatments in various cancers also reduced cell migration and epithelial-mesenchymal transition (EMT), which are crucial for the aggressiveness and cancer stem cell (CSC) properties of tumor cells." (PMID 40133683, 2025). "Based on these data, FASN was specifically overexpressed in cancer tissues and adjacent tissues." (PMID 40995612, 2025). "As a result, FASN has been recognized as a potential therapeutic target for cancer treatment." (PMID 41196069, 2025). "Furthermore, previous studies have shown that key enzymes such as ACC1 and FASN are significantly upregulated in multiple cancer types, and their elevated levels are strongly correlated with accelerated cell proliferation." (PMID 39425259, 2025). "FASN is a key enzyme in the de novo synthesis of fatty acids and is involved in energy storage, membrane biosynthesis, and the generation of signaling mediators, which are critical for cancer development during tumorigenesis." (PMID 40148316, 2025).